TNF (tumor necrosis factor)
Diseases named in the same sentence as TNF in open-access papers (continued):
Sharing a sentence is not in itself a finding about the gene and the disease.
Sepsis (continued). "Attime of diagnosis, serum IL-1β, IL-6, IL-8, and TNF-α levels of culture-provensepsis were significantly higher than those of the control groups (P<.05);but only serum IL-8 levels of culture-proven sepsis was significantly higherthan culture-negative sepsis (P<.05)." (PMID 18274637, 2007). "Thus it is not surprising that anti-TNF antibody, by removing inhibitory pressure from the pathogen, can enhance the disease in falciparum malaria, as shown five years earlier in human sepsis." (PMID 17029647, 2006). "However, although in some cases of sepsis in humans (e.g. meningococcal disease) elevated serum levels of TNF-α have been found in up to 90% of patients, several other clinical studies in septic patients reported only minimally elevated or undetectable levels of TNF-α." (PMID 15774049, 2005). "Unlike early inflammatory mediators, such as TNF‐a, HMGB1 is considered to be a late mediator contributing to lethal systemic inflammation within cytokine‐mediated sepsis animal models." (PMID 41551210, 2026). "TNF, IL-18, IL-10, IL-1Ra and s-CHI3L1 were significantly higher in the septic shock group, compared with the sepsis and non-sepsis groups." (PMID 40681771, 2025). "○Enhanced antibacterial and antibiofilm activity against Gram‐positive and negative bacteria.○Reduction in the levels of TNF‐α, IL‐1β and IL‐6 in CLP model.○Effective reduction of sepsis‐induced multiple organ damage.○Improved survival rates." (PMID 40599085, 2025). "AKI patients showed increases in sepsis-related organ failure assessment (SOFA) score, BUN, Scr, TNFα and IL-1β levels compared to non-AKI patients." (PMID 41406481, 2025). "IL-1beta, IFN-α2, IFN-γ, TNF-α, IL-8, IL-33, IL12p70, IL-17A, and IL-23 do not show significant differences between the sepsis groups or compared to healthy controls at d0, suggesting these markers may not play a central role in distinguishing between sepsis types." (PMID 40510342, 2025). "Accordingly, aging induction by D-gal worsened sepsis severity only in renal and liver injury, but not mortality, encephalopathy (SHIRPA score), and serum cytokines (IL-6 and TNF-α)." (PMID 39423218, 2024). "Although satisfactory results have been obtained in animal models for blocking cytokine activity such as TNF-α, IL-17, and IL10, the results in clinical trials on patients with sepsis are not clear." (PMID 38313013, 2024). "While the interaction between TNF and IL-18 had not been reported to our knowledge, TNF plus IFN-γ38–41 or IL-1β42–44 worsen the outcome of sepsis and other inflammatory disorders in vivo." (PMID 38191855, 2024). "The levels of TNF‐α in both cortex and hippocampus were elevated at day 1 post‐surgery and were dramatically decreased in AQP4 knockout mice, but not at day 7 after sepsis onset in cortical tissue." (PMID 36922751, 2023). "We found increased levels of IL-1ra, IL-6, IL-8, IL-13, TNF-α, IP-10, MCP-1, MIP-1α, and G-CSF in both, COVID-19 negative and COVID-19 positive sepsis patients, as compared to healthy controls." (PMID 36980378, 2023). "Towards this goal, a recent study demonstrated that diminished production of both tumor necrosis factor (TNF) and interferon (IFN)γ following ex vivo stimulation of whole blood from septic patients distinguished between sepsis survivors and non-survivors." (PMID 37831231, 2023). "More than 30 clinical trials have shown no beneficial effects of immunosuppressive therapies on sepsis, including anti-endotoxin molecules, TLR-receptor antagonists, anti-cytokine therapies (e.g., anti-TNF-α, IL-1Rα), and high dose corticosteroids." (PMID 37144032, 2023). "Similarly, the levels of TNF-α, IL-6, TGF-ß1, and NF-κB significantly increased in the model group and decreased in the Tα1, VitC, and Tα1 + VitC groups, indicating that combined Tα1 and VitC therapy may help regulate the immunological state of patients with sepsis, thereby improving prognosis." (PMID 36816800, 2023).
Sepsis (continued). "After inducing sepsis by cecal ligation and puncture (CLP), HDC-knockout mice exhibited reduced plasma histamine levels, and the increase in TNFα, IL‐1b, IL‐6 and MCP1 levels in sepsis were attenuated when there was a lack of plasma histamine." (PMID 36823620, 2023). "This is characterized by elevated levels of inflammatory cytokines, such as interleukin (IL), interferon (IFN), chemokine, tumor necrosis factor (TNF), and colony-stimulating factor (CSF), but there are currently no effective drugs to treat sepsis-induced ALI." (PMID 37175637, 2023). "To examine whether the failure to shed TNFα from peripheral circulating leukocytes contributes to the sex-specific differences in cardiac inflammation in early sepsis, we examined polymicrobial sepsis in iRHOM2−/− mice, for which there is no sexual dimorphism reported." (PMID 35723764, 2022). "Hence, we hypothesized that sepsis molecules (LPS, cytokines, and some viable bacteria) pass through the damaged BBB and upregulate miR370-3p in brain cells, partly through the activation of TNF-α receptor (TNFR) and TLR-4 by TNF-α and LPS, respectively, that enhance mitochondrial injury." (PMID 35628259, 2022). "Immunotherapeutic drugs such as TNF- and TLR-4, which have been reported in foreign studies, have been used on a small scale in the clinic, bringing new hope for the treatment of sepsis, but no successful efficacy has been achieved thus far." (PMID 35982998, 2022). "Myocardial stress/injury after early sepsis is limited in females, with less cardiac infiltration of CD4 + leukocytes but independent of shedding of TNFα from peripheral circulating leukocytes." (PMID 35723764, 2022). "Consistent with the inability of iRHOM2−/− mice to cleave TNFα, iRHOM2−/− mice of both sexes also failed to shed CD62L, a key selectin that is rapidly shed and detected at elevated levels in the plasma during sepsis and correlates with survival." (PMID 35723764, 2022). "Aged sepsis-survivor rats displayed a decreased object discrimination index, elevation of NGAL levels and Fe2+/Fe3+ ratio, and no TNFα responses." (PMID 34997032, 2022). "In agreement, iRhom2-deficient mice show no evident abnormalities, but they are protected against sepsis, RA, lupus nephritis and hemophilic arthropathy, majorly due to blocking the iRhom2/ADAM17/TNF pathway." (PMID 33579029, 2021). "By contrast, different cytokines participate in sepsis progression, with increased levels of IL-1β, IL-6, IL-8, IL-12, IFN-γ, granulocyte colony-stimulating factor, and TNF-α observed in non-survivors as compared to survivors." (PMID 34884813, 2021). "BM-MSCs from TNF-α or TNF-R1 knockout mice did not protect against caecal ligation and puncture-induced sepsis following intravenous administration." (PMID 34831203, 2021). "Narciclasine treatment showed significant reduction of inflammatory cytokines (TNF-α, IL-6, IL-1β and IFN-γ) in liver homogenates compared to the sepsis group without treatment." (PMID 32076015, 2020). "In contrast, the levels of TNF-α, IL-12p40, IFN-α, IFN-γ, IL-17, and IL-4 in the sepsis patients were not significantly different from those in the healthy controls." (PMID 32826331, 2020). "Treatment with narciclasine significantly reduced the levels of inflammatory cytokines TNF-α, IL-6, IL-1β and IFN-γ in lung homogenates when compared to the sepsis group without treatment." (PMID 32076015, 2020). "The results showed high levels of proinflammatory cytokines TNF-α and IL-6 in BALF of sepsis mice without b-AP15 treatment when compared with controls." (PMID 32391376, 2020). "Simvastatin treatment was able to reduce the levels of TNF-α, IL-6, MIF, and IL-1β 24 hours after sepsis induction, indicating an important negative immunomodulary effect of simvastatin in this model." (PMID 33110395, 2020). "Sepsis, but not PAB, led to increase in endothelial damage marker PAI-1 and cytokines TNF and IL-6 (all p<0.05) in plasma." (PMID 31247004, 2019).
Sepsis (continued). "Our data showed that genetic deficiency of Il-33 prevented ILC2 expansion in the lung and increased MLEC death following CLP-induced sepsis; and addition of IL-33 into MLEC did not affect MLEC death in response to LPS and TNFα." (PMID 29511181, 2018). "Nevertheless neither TNF or IL-1β have emerged as reliable biomarker for hyperinflammation in sepsis patients, potentially because they are elevated only for a very short period of time in the initial phase of sepsis, when patients may not yet have been admitted to the ICU." (PMID 30233566, 2018). "As anti-inflammatory treatments in humans with antibodies to TNF-α or IL1-β resulted disappointing, cytokine modulation approaches were discouraged and neutralization of IFN-β has not been pursued for sepsis treatment." (PMID 28533774, 2017). "Thrombocytopenic mice are associated with a higher systemic bacterial load, increased plasma levels of pro-inflammatory cytokines (TNFα, IL-6, and IFN-γ) and accordingly a poorer outcome of sepsis induced by Gram-negative bacteria." (PMID 28428949, 2017). "Nevertheless, in sepsis with AKI, plasma NGAL and tumor necrosis factor alpha (TNFα) were already elevated at 6 hours without changes to serum creatinine and blood urea nitrogen, while IL-6 and IL-10 are increased only after 24 hours." (PMID 26880194, 2016). "However, Cobalt alloy particle induced inflammatory responses as determined by IL-1β and TNF-α secretion in vitro were not as pro-inflammatory relative to TLR4 PAMP agonist despite high levels of PAMP agonist (LPS) used at levels corresponding to sepsis (>500pg/mL)." (PMID 27467577, 2016). "Due to this fact, the use of corticosteroids, antagonists of tumor necrosis factor (TNF), and antagonists of interleukin 1 receptor does not have good results in treating sepsis." (PMID 26221578, 2015). "On the other hand, the same study based on heart tissue demonstrated a significant reduction in lipid peroxidation products and TNF-α, but not in H2O2 concentration, after BQ123 administration in experimental sepsis." (PMID 25288367, 2015). "Cytokine levels TNF, IL-6 and IL-10 were highest in CAP (82%) with fatal severe sepsis and lowest in CAP with no severe sepsis." (PMID 24363503, 2013). "The neutralization of inflammatory mediators with endotoxin-specific antibodies, tumor necrosis factor (TNF) inhibitors, or interleukin receptor antagonists does not improve the overall survival of people with sepsis." (PMID 24062788, 2013). "A detectable level of these markers was more common in patients with sepsis than patients with non-infective SIRS: IL1β 61% vs 15%, GMCSF 26% vs 1% and TNFα 3% vs 0%." (PMID 23531337, 2013). "The elevation of TNF-α production does not seem to correlate with severity of clinical status in both sepsis and SIRS critically ill patients, making the elevation of TNF-α production seems not to be an independent predictor in patients with sepsis." (PMID 24175285, 2013). "It is noteworthy that the four largest clinical studies evaluating novel therapies in patients with sepsis – evaluating drotrecogin alpha, tissue factor pathway inhibitor, antithrombin III, and monoclonal antibodies to TNF – did not specify hemodynamic goals." (PMID 17584921, 2007). "In the CLP-induced sepsis model, pathological browning of WAT in non-obese mice is triggered via multiple pathways: sepsis-induced inflammatory factors (TNF-α, IL-6) drive M2 macrophage polarization, and the catecholamines secreted by M2 macrophages activate β-3ARs on adipocytes." (PMID 41498391, 2026). "Compared with patients without sepsis, peripheral blood monocytes and BALF AMs from patients with sepsis exhibited lower human leukocyte antigen‐D related (HLA‐DR) expression and lower TNF‐α and lactate production after in vitro LPS stimulation." (PMID 41178622, 2026).
Sepsis (continued). "The TNF-α (11.42 ± 9.39 vs. 20.17 ± 14.85) and fecal calprotectin levels (23.87 ± 17.96 vs. 53.99 ± 29.49) of the SAE group were significantly higher than those of the non-SAE sepsis group." (PMID 40529149, 2025). "During sepsis (resulting from severe infection mostly with Gram-negative bacteria), platelets become overactivated and release PEVs containing numerous molecules and DAMPs, such as HMGB1, proinflammatory cytokines (IL-1β, TNF-α, IL-6) and chemokines (MCP-1)." (PMID 37559007, 2023). "As such, there was an enhanced severity of sepsis in macrophage-depleted mice with CLP compared with CLP in the Lipo group, as indicated by the survival analysis, leaky gut, serum cytokines (TNF-α and IL-10, but not IL-6), serum creatinine, and alanine transaminase." (PMID 38132765, 2023). "Serum samples of sepsis patients (as compared to non-septic patients) contained higher neutrophil counts (13.3 × 109 vs. 6.5 × 109 cells/l) and higher concentrations of MPO (13.1 vs. 8.8 ng protein/mL), IL-6 (188 vs. 23 pg/mL), and TNFα (348 vs. 63 pg/mL)." (PMID 32050431, 2020). "Propranolol (group B) but not esmolol (group D) administration resulted in elevated TNF-α levels, comparable to those observed in group A. In conclusion, antecedent administration of EPI in a rat sepsis model inhibits the production of TNF-α possibly via the β2-adrenoceptor." (PMID 29984678, 2020). "However, its protective effect on TNF-α/JNK-induced hepatocyte apoptosis and on liver injury in sepsis by inhibiting TLR4/NF-κB/JNK pathways was not fully addressed." (PMID 32457606, 2020). "To determine whether GSS inhibits sepsis-induced inflammatory response and ALI via lung vascular ECs, we further check the expression and secretion changes of TNF-α and IL-6 in ECs with and without LPS stimulation." (PMID 32082076, 2019). "Although studies reported that the levels of IL-6 and TNF-α decreased with time, there is currently no consensus to guide clinicians in terms of controlling the levels of inflammation and DAMPs in AKI patients with sepsis managed through CRRT." (PMID 30666251, 2018). "However, as expected and in stark contrast to sepsis, NSI neither induced symptoms of illness nor systemic increases of inflammatory cytokines such as IFN-γ, MCP-1 or TNF." (PMID 29415028, 2018). "The findings of the present study suggest that BML-111 markedly decreases the levels of inflammatory cytokines without changing the level of TNF-α in the blood, and also reduces the activation of glias, the number of TUNEL-positive cells, and cognitive impairment in the brains during sepsis." (PMID 30186119, 2018). "However, in the lipopolysaccharide (LPS) model of sepsis, while overexpression of PPAR-γ in cardiomyocyte prevents septic cardiac dysfunction, cardiac mRNA levels of interleukin 1β (IL-1β), IL-6, and TNF-α are not reduced." (PMID 28845215, 2017). "IL-6 has the best discriminative power in sepsis and non-infectious SIRS, with sensitivity above 80% and specificity above 70%, which is higher than conventional inflammatory markers including CRP and TNF-α." (PMID 24341820, 2013). "Nonsurviving sepsis patients had lower levels of MMP-9 (P = 0.037), higher levels of TIMP-1 (P < 0.001), lower MMP-9/TIMP-1 ratio (P = 0.003), higher levels of IL-10 (P < 0.001), and lower TNF-α/IL-10 ratio than did surviving patients." (PMID 19799791, 2009). "Although robust TNF-α responses are vital for combating Gram-negative bacteria, an excessive TNF-α response can lead to harmful consequences, including autoimmune diseases and potentially fatal conditions, such as sepsis, septic shock, tissue damage, and death." (PMID 41157245, 2025). "In gram-negative sepsis, LPS and tumor necrosis factor (TNF-α) both induced apoptosis of glomerular endothelial cells, in renal endothelial cells, TNF-α Receptor 1 induces apoptosis via a caspase-8-dependent pathway, and may promote sepsis-induced AKI in vivo." (PMID 35655858, 2022).
Sepsis (continued). "Consequently, delayed administration of EGCG did not affect circulating levels of TNF at late stage of sepsis, but specifically attenuated systemic accumulation of HMGB1, as well as IL-6 and KC-two most reliable surrogate markers of lethal sepsis." (PMID 17987129, 2007). "However, whether TNF-α inhibition would be beneficial to the glycocalyx in the often more severe inflammation observed in critically ill patients is undetermined, although the history of TNF-α inhibition trials in sepsis would suggest not." (PMID 35872762, 2022). "However, the most remarkable is the increase of IL-1β, IL-6, IFN-γ, and TNF-α expression in the hippocampus and IL-6, IL-17, and IFN-γ in the PFC 10 days after CLP surgery when the blood culture was negative, and the animals presented a full recovery from sepsis." (PMID 35606817, 2022). "Importantly, the LPS-induced upregulation of both TNF-α and iNOS observed in sham PM was not significantly diminished in IRAK-M−/− macrophages recovered 24 hrs post CLP, indicating that in the absence of IRAK-M, these cells were resistant to the development of a “tolerized” phenotype during sepsis." (PMID 20585389, 2010). "Indeed, TNF-α, IL-6, white cell blood count, C-reactive protein or procalcitonin did not correlate with serum ghrelin concentrations neither in all ICU-patients, nor in the subgroups of sepsis and non-sepsis patients in the clinical setting at admission to the Medical ICU (data not shown)." (PMID 20500817, 2010).